INS (insulin)
Diseases named in the same sentence as INS in open-access papers (continued):
Sharing a sentence is not in itself a finding about the gene and the disease.
Glucose intolerance (continued). "Male offspring from RUPP dams at PND60 exhibited significantly lower circulatory insulin concentrations concomitant with a reduction in pancreatic insulin contents and glucose intolerance than the male offspring of the sham group." (PMID 36109770, 2022). "Congruently, the implantation of hypothalamic stem cells with impaired IKK/NF-κB signaling in HFD-fed mice increases neurogenesis and POMC neuronal differentiation, and reduces body weight, food intake, glucose intolerance and insulin levels." (PMID 35112705, 2022). "β cell-specific Cdkal1 KO mice display glucose intolerance and impaired insulin secretion, along with elevated markers of ER stress." (PMID 35008927, 2022). "Reduction in insulin-mediated glucose disposal leads to compensatory hypersecretion of insulin to maintain homeostasis, and glucose intolerance results if the endocrine pancreas response is insufficient." (PMID 35455055, 2022). "Single and long-term treatment with EREG effectively rescued glucose intolerance in comparative insulin and EREG tolerance tests in Lepob mice." (PMID 35159237, 2022). "For example, in ob/ob mice, FBXW7 expression decreases blood glucose and insulin levels, IR and glucose intolerance, and prevents expression of lipogenic genes and triglyceride accumulation." (PMID 35055338, 2022). "Animals genetically deprived of adipsin have glucose intolerance due to insulinopenia; isolated islets of these mice have reduced insulin secretion when stimulated by glucose." (PMID 35327350, 2022). "In vivo, celastrol administration resulted in the alleviation of glucose intolerance and insulin insensitivity assessed by intra-peritoneal glucose tolerance test (GTT) and insulin tolerance test (ITT) in DIO mice, respectively." (PMID 36009315, 2022). "Inhibition of Cl−loaders such as Nkcc1 (Slc12a2) and others (Nkcc2, Slc12a1) with loop-diuretics bumetanide or furosemide impaired islet insulin secretion in vitro and resulted in glucose intolerance in different mouse models." (PMID 36580474, 2022). "Enhanced MR signaling also induces an impairment in hepatic insulin metabolic signaling which contributes to hepatic glucose intolerance and increased hepatic gluconeogenesis." (PMID 36012219, 2022). "The UOX-KO mice exhibited glucose intolerance and insulin insensitivity compared to the WT mice, as assessed by GTT or ITT." (PMID 36177037, 2022). "This study provides novel findings on the effect of the SGAs olanzapine and aripiprazole in inducing glucose intolerance and reducing insulin secretion." (PMID 34932133, 2022). "Systemic inflammation damages the pancreatic β cells, disrupts insulin action and mediates glucose intolerance." (PMID 36014875, 2022). "Ellagic acid works as an anti-diabetic agent by stimulating insulin secretion and decreasing glucose intolerance in pancreatic ß-cells." (PMID 35308202, 2022). "In fact, when such endocytosis is impaired, the β-cell dysfunction is unable to secrete insulin in response to increased glucose concentrations, leading to glucose intolerance, as demonstrated in mice." (PMID 35625916, 2022). "In contrast to this model, ubiquitous chemerin knockout reduced glucose-stimulated insulin secretion and induced glucose intolerance while hepatic chemerin overexpression improved both of these measures." (PMID 35052810, 2022). "Ample evidence shows that ghrelin inhibits insulin secretion in animals, and the blockade of ghrelin enhances insulin secretion and ameliorates the development of diet-induced glucose intolerance." (PMID 35454106, 2022). "Mice with specific deletion of FAM3A in pancreatic β cells exhibit markedly impaired insulin secretion and glucose intolerance." (PMID 35800345, 2022). "The two predominant defects in the pathogenesis of glucose intolerance are beta-cell dysfunction and reduced insulin sensitivity." (PMID 34561756, 2022).
Glucose intolerance (continued). "For example, exogenous chemerin treatment of diabetic db/db mice lowered serum insulin levels and augmented glucose intolerance." (PMID 35052810, 2022). "With Dox exposure, both male and female β-tetO-NICD mice developed profound glucose intolerance, accompanied by impaired glucose-stimulated insulin secretion (GSIS)." (PMID 35167496, 2022). "Muscle-specific SHP2 invalidation resulted in reduced insulin-evoked glucose uptake in skeletal muscle and systemic insulin and glucose intolerance." (PMID 36140242, 2022). "TfebΔβ-cell mice showed aggravation of HFD-induced glucose intolerance and impaired insulin release." (PMID 35288580, 2022). "Treatment of female mice with olanzapine or aripiprazole for 6 months induced weight gain (p<0.01 and p<0.05, respectively), glucose intolerance (p<0.01) and impaired insulin secretion (p<0.05) vs mice fed a control chow diet." (PMID 34932133, 2022). "In particular, very long-chain sphingolipid species (C < 22) are known to protect against glucose intolerance and hepatic insulin resistance development." (PMID 35444259, 2022). "Here, we showed that AT1aR gene knockout improved glucose intolerance and insulin sensibility in high-fat diet induced obese rats." (PMID 35802723, 2022). "GPR92-KO mice exhibited glucose intolerance and reduced insulin levels — despite the enlarged pancreatic islets — as well as increased islet macrophage content and inflammation level compared with WT mice." (PMID 36066975, 2022). "IFG, either as an isolated feature or combined with glucose intolerance, is strongly connected to a weakened 1st-phase insulin secretion capacity." (PMID 36432409, 2022). "They spontaneously develop early glucose intolerance accompanied by impaired glucose-stimulated insulin secretion and increased hepatic glucose production during the postweaning period." (PMID 36359885, 2022). "In mouse models, it has been reported that the suppression with polyclonal antibodies against selenoproteins P improves glucose intolerance and insulin secretion." (PMID 36141277, 2022). "Studies have indicated that adipsin improves the maintenance of β-cell function as adipsin knockout mice exhibit glucose intolerance due to insulinopenia while replenishment of adipsin boosts their insulin secretion." (PMID 35909516, 2022). "While we did not detect changes in mesenteric fat, we have previously reported diabetogenic (increased fasting glycemia and glucose intolerance, insulin insensitivity) and exaggerated pressor responses in adult offspring of DE-71 exposed dams." (PMID 36277707, 2022). "Recently, we demonstrated abnormal glucose intolerance owing to impaired insulin secretion in a glucose tolerance test with 8-week-old male SDC4-KO mice of the C57BL/6J (B6) strain." (PMID 36292936, 2022). "Another study showed that supplementation with E2 in ovariectomized C57BL/6J mice resulted in improved glycemia, glucose intolerance, insulinemia, and insulin secretion." (PMID 35743136, 2022). "We found that p20 rats of both sexes have elevated blood glucose and insulin levels, low systemic insulin sensitivity, and glucose intolerance." (PMID 36224569, 2022). "Banxia Houpu decoction is believed to restore glucose intolerance in CUMS rats by improving insulin signaling and suppressing NLRP3 inflammasome activation in the liver and brain." (PMID 35957821, 2022). "This study utilising improved assay technology re-affirms that beta-cell dysfunction is evident throughout the spectrum of glucose intolerance, whereas the predominant fall in insulin sensitivity occurs early in its evolution." (PMID 34561756, 2022). "Consistently with this idea, patients with Tangier disease are characterized by an impaired HDL-mediated lipid efflux and concomitant glucose intolerance and decreased insulin secretion." (PMID 35625916, 2022). "The two predominant pathophysiological defects resulting in glucose intolerance are beta-cell dysfunction and insulin insensitivity." (PMID 34561756, 2022).
Glucose intolerance (continued). "We further demonstrated that hyperuricemia evoked glucose intolerance in liver macrophages, induced IR, and impaired insulin signaling." (PMID 36177037, 2022). "Consisted with the previous literature, we found maternal HF feeding increased body weight, blood glucose, and insulin and induced glucose intolerance in male offspring at weaning." (PMID 35928844, 2022). "We found that exposure to HG induces a state of glucose intolerance, which was significantly attenuated by insulin treatment." (PMID 36430296, 2022). "The current study suggests a positive impact on insulin secretion, body composition, and exercise capacity that will likely result in improved clinical outcomes in patients with CF and glucose intolerance." (PMID 35328985, 2022). "In heterozygous eNOS+/− mice, fed with either standard or high fat diet (HFD), blood insulin increase in response to a glucose load is impaired, combined with overt glucose intolerance and insulin resistance upon HFD." (PMID 35986504, 2022). "Under metabolic stress (HFD), OGA deletion led to improved GTT and normal insulin secretion in male mice, and glucose intolerance in females despite improved insulin secretion in vivo." (PMID 36387851, 2022). "Adipocyte-specific Blnc1-knockout (AKO) mice displayed an increased glucose level, insulin level, glucose intolerance and IR as well as more serious hepatic steatosis after HFD feeding." (PMID 36555704, 2022). "Inhibition of IDE activity with a small molecule, was shown to result in glucose intolerance suggesting a physiological role for IDE in insulin clearance." (PMID 36396721, 2022). "Although the adipokines leptin and adiponectin improve insulin sensitivity, others contribute to the development of glucose intolerance, including visfatin, fetuin-A, resistin, and plasminogen activator inhibitor-1 (PAI-1)." (PMID 35056647, 2022). "For instance, K supplements had favourable impacts on insulin sensitivity and improved glucose intolerance during low serum K." (PMID 36432472, 2022). "Consisting with the reduced body fat mass in Ddr2Adipo mice on HFD, Ddr2Adipo mice are protected from HFD-induced glucose intolerance, and exhibit enhanced clearance of glucose following insulin challenge." (PMID 34645939, 2022). "Increased intestinal permeability facilitated the LPS translocation into the circulation and triggered inflammation, which deteriorates insulin signaling in pregnant women, leading to glucose intolerance." (PMID 36144203, 2022). "We found that both male and female p20 rats have elevated levels of glucose and insulin, low systemic insulin sensitivity, and glucose intolerance." (PMID 36224569, 2022). "Supplementation with eugenol effectively corrected the glucose intolerance (by 26.32%) and insulin sensitivity (by 22.41%) declines in T2DM mice." (PMID 36424928, 2022). "Augmented Hh signaling resulted in impaired β-cell function and insulin secretion leading to glucose intolerance in double transgenic mice." (PMID 35832432, 2022). "While compelling evidence supports that FFAR3 ablation reduces insulin secretion and hence induces a marked glucose intolerance, others have found that FFAR3−/− mice exhibit improved glucose homeostasis." (PMID 36362376, 2022). "Hyper-O-GlcNAcylation appeared to have no impact on glucose tolerance until 28wks of age, where the animals develop glucose intolerance in part due to reduced glucose stimulated insulin secretion." (PMID 36387851, 2022). "The offspring had glycometabolic disorders, such as glucose intolerance and IR, at 12 weeks of age and reduced insulin levels at birth." (PMID 36438765, 2022). "In contrast, the glucose intolerance and insulin responsiveness were aggravated in lSptlc2-Tg mice fed a HFD compared with those in WT mice fed a HFD." (PMID 35513574, 2022).
Glucose intolerance (continued). "In the light of our previous and present observations, it is reasonable to conclude that a chronic increase in muscle [Ca2+]i diminishes muscle responsiveness to insulin-glucose uptake and subsequently provokes muscle glucose intolerance." (PMID 35547584, 2022). "Its over-expression can produce glucose intolerance in animal models, due to impaired insulin production and secretion from pancreatic β-cells." (PMID 34574169, 2021). "EGCG and caffeine, the most abundant ones, were probably the main responsible for the glucose intolerance decrease and insulin sensitivity increase." (PMID 34202230, 2021). "For example, β cell-specific furin gene knockout mice developed glucose intolerance and had smaller islets with lower insulin content than wild controls." (PMID 35046896, 2021). "Pancreatic deletion of GRK2 in mice resulted in glucose intolerance with diminished insulin secretion." (PMID 34045505, 2021). "We further demonstrated that offspring of obese dams developed sex-differences in glucose intolerance and islet insulin secretion." (PMID 34108935, 2021). "In conclusion, our data showed that excessive sodium chloride intake was associated with glucose intolerance under HFD conditions by attenuating HFD-induced β-cell proliferation and β-cell mass expansion with the impairment of insulin secretion." (PMID 33730054, 2021). "Decreases in Gys and Glut1 would reduce glucose uptake and storage, contributing to whole-body glucose intolerance, as muscle accounts for >70% of insulin-stimulated glucose use." (PMID 34419449, 2021). "For instance, oral administration of luteolin reversed glucose intolerance improving insulin sensitivity in an insulin-resistant mouse model." (PMID 34594472, 2021). "Preclinical studies using genetic knock out animals also showed that the disruption in pancreatic islet HSG resulted in glucose intolerance and decreased islet insulin secretion." (PMID 34108935, 2021). "Other studies showed that HIF induction can enhance hypothalamic glucose sensing, and the inhibition of hypothalamic HIF1 lead to glucose intolerance and increased serum insulin level." (PMID 34733235, 2021). "In line with that, β-cell specific Cdkal1 knockout (KO) mice showed marked glucose intolerance and impaired insulin secretion that was exacerbated by high fat feeding." (PMID 33419045, 2021). "Dysregulated ISG biogenesis leads to glucose intolerance in vivo, while increased proinsulin / insulin ratios are archetypical of diabetic patients and indicative of impaired processing within immature ISG." (PMID 33946444, 2021). "On the other hand, pancreatic beta cell-specific Rab3GEP knockout mice display glucose intolerance with reduced insulin secretion, which is seen in Rab3a- and Rab27a-dificient mice." (PMID 34483204, 2021). "Amongst those with features of glucose intolerance, the differences in insulin iAUC between breads were amplified compared with the findings from the primary analysis." (PMID 34444739, 2021). "The absence of gut microbiota in germ free mice or depletion of microbiota by antibiotics treatment in WT and diet induced obese mice not only reduced glucose and insulin levels but also improved glucose intolerance and insulin insensitivity." (PMID 35008623, 2021). "Accordingly, there was a corresponding down-regulation of IRS1 and phospho-AKT levels in their liver and skeletal muscle tissues, which correlated with impaired insulin sensitivity and glucose intolerance." (PMID 34574169, 2021). "In general, serum or plasma insulin levels are elevated relative to the severity of glucose intolerance." (PMID 33799894, 2021). "Transgenic mice with adipose tissue-specific Angptl4 overexpression exhibited glucose intolerance and impaired insulin sensitivity in skeletal muscle, as well as aggravated hepatic steatosis when subjected to long-term HFD feeding." (PMID 34944728, 2021).
Glucose intolerance (continued). "Lastly, many studies have identified MCP-1 as an insulin-responsive cytokine that promotes IR and glucose intolerance." (PMID 33671853, 2021). "Pancreatic deletion of 12-LO protects obese HFD fed mice from glucose intolerance and improves insulin secretion in cytokine-treated islets in a 12-HETE-dependent manner." (PMID 34943862, 2021). "That study showed that these mice have glucose intolerance with impaired increase in insulin levels only after a large glucose load (75 and 100mg), but not after smaller glucose loads (25 and 50mg)." (PMID 34122340, 2021). "Adult male and female offspring of dams fed low-protein diet during pregnancy display glucose intolerance despite increased insulin sensitivity in peripheral tissues in part due to impaired β cell dysfunction." (PMID 34032632, 2021). "Previous studies have shown that GF mice fed a HF diet have lower fasting blood glucose and circulating insulin and they are protected from glucose intolerance." (PMID 33222397, 2021). "The findings in our doxepin-treated mice are consistent with previous findings regarding aggravated glucose intolerance and decreased insulin levels." (PMID 33809508, 2021). "Exposure during pregnancy in women causes glucose intolerance and high levels of insulin, triglycerides, and leptin in plasma compared to the control group, which seems to indicate that exposure to BPA during pregnancy promotes glucose intolerance." (PMID 34200822, 2021). "More striking is the fact that islets lacking gap junctions have statistically normal insulin levels and insulin sensitivity, despite glucose intolerance due to altered dynamics of insulin secretion." (PMID 33986325, 2021). "Chronic high glucose conditions can induce oxidative stress by several mechanisms, such as, glucose autoxidation, polyol pathway, AGE formation, and PKCβ1/2 kinase, worsening glucose intolerance and impairing insulin signaling." (PMID 34531992, 2021). "Aged females developed glucose intolerance and had reduced glucose-stimulated insulin secretion following nearly nine months of high-fat feeding in postnatal life." (PMID 34436455, 2021). "In patients who developed NODAT under tacrolimus, an improvement of glucose intolerance and insulin discontinuation was obtained after conversion to belatacept." (PMID 33800138, 2021). "Conversely, in some individuals with Wilson’s disease, glucose intolerance with concomitant hyperactive insulin production was noted and this abated following treatment with penicillamine." (PMID 34836302, 2021). "The difference in male and female MatOb offspring glucose intolerance indicates the possibility of sex-specific differences in pancreatic islet insulin secretion at P21, which is determined by total islet β cell mass and islet insulin secretion." (PMID 34108935, 2021). "Both GPRC6A-/- and OCN-/- mice show similar phenotypes, including exacerbated glucose intolerance and impaired insulin secretion." (PMID 34489478, 2021). "The present study shows that treatment with rhTM ameliorated glucose intolerance in diabetic mice by protecting insulin-producing cells from apoptosis." (PMID 34571886, 2021). "The high-fat fed animals also presented superior insulin and glucose intolerance, as evidenced by lower constant for insulin tolerance test (kITT) and higher area under the curve (AUC) in the glucose tolerance test (GTT) when compared to their CTLs." (PMID 34552556, 2021). "CaV1.3 deletion reduced insulin release at lower glucose concentration and, due to smaller β-cell mass, also reduced the total insulin release, thereby leading to glucose intolerance in mice." (PMID 34440773, 2021). "Mice infected with S. mansoni reduced body weight by improving insulin sensitivity and glucose intolerance." (PMID 34901005, 2021).